SMAD7 (SMAD family member 7)
Diseases named in the same sentence as SMAD7 in open-access papers (continued):
Sharing a sentence is not in itself a finding about the gene and the disease.
melanoma (23 papers, 2008 to 2025). A malignant, usually aggressive tumor composed of atypical, neoplastic melanocytes. "In breast and melanoma tumors, increased levels of Smad7 are associated with a better outcome, while in colon and hepatic cancer, increased levels of Smad7 are associated with worse outcome." (PMID 25501935, 2014). "Another in vivo study showed that SMAD7 overexpression inhibited the lung metastasis of melanoma cells." (PMID 36550779, 2023). "SMAD7 was defined as a marker of aggressive tumour behaviour and poor clinical outcome in melanoma patients." (PMID 37685308, 2023). "In melanoma, SMAD7 expression was assessed by immunohistochemistry in 205 cutaneous melanoma primary tumours and the results were correlated with the clinicopathological features of the patients." (PMID 37685308, 2023). "Of note, stable overexpression of SMAD7 in melanoma cells produced less bone metastases in a mouse model of bone metastasis and this effect was TGFβ-dependent." (PMID 32545415, 2020). "A neutralizing pan-TGF-β antibody reduced tumor burden and osteolytic lesions in a mouse model of bone metastasis, and overexpression of TGF-β-signaling inhibitor Smad7 in a mouse model delayed the establishment and the growth of melanoma bone metastases." (PMID 29156807, 2017). "Blocking receptor function by over-expression of the natural inhibitor SMAD7 extended survival of mice xenografted with SMAD7 expressing melanoma cells." (PMID 27835901, 2016). "We have previously reported that stable expression of Smad7 in human colon adenocarcinoma FET cells induces tumorigenicity, whereas Smad7 inhibits tumorigenicity in melanoma cells." (PMID 18781153, 2008). "Furthermore, high SMAD7 expression independently predicted unfavourable outcomes: melanoma-specific survival (hazard ratio = 3.16, p < 0.001) and recurrence-free survival (hazard ratio = 2.88, p < 0.001)." (PMID 37685308, 2023). "CERS4 expression was down-regulated in metastatic (late stage) head and neck squamous cell carcinoma (HNSCC), renal cell carcinoma, and melanoma, indicating that activation of CerS4/ceramide-Smad7 could target and inhibit tumor cell migration and invasion." (PMID 33996533, 2021). "The TGF-β signal is important for the metastatic capacity of melanoma to bone, and both overexpression of SMAD7 (inhibitory SMAD) and the use of chemical inhibitor have been shown to be efficient in the inhibition of melanoma cells invasion into the bone in athymic nude mice experimental model." (PMID 23984088, 2013). "While previous studies showed that overexpression of the TGFβ signaling inhibitor SMAD7 reduced the proliferation and metastatic potential of the 1205Lu melanoma cell line, other studies suggested that TGFβ itself could inhibit tumor cell migration and metastasis." (PMID 38201651, 2024). "Recently, conditional deletion of Smad7, a negative regulator of TGF‐β/SMAD pathway, led to sustained melanoma growth and at the same time promoted metastasis formation, confirming that TGF‐β/SMAD pathway is a promising target for melanoma." (PMID 33724679, 2021). "In human melanoma cells, constitutive SMAD2/3 signaling is mitigated by SMAD7 stable overexpression, resulting in decreased cell invasion and secretion of MMP-9/MMP-2." (PMID 29799477, 2018). "In melanoma cells, constitutive SMAD signaling occurs in response to autocrine TGF-β secretion, and experimental blockade of TGF-β signaling by SMAD7 overexpression dramatically reduces their tumorigenic and metastatic potential." (PMID 21211030, 2011). "SMAD7 overexpression alters 1205Lu melanoma cell tumorigenicity and metastatic potential without altering SKI levels." (PMID 21211030, 2011).
diabetes (21 papers, 2011 to 2025). "Whole grain products were associated with a CpG, annotated to SMAD7, which has a mechanistic role in the protection of the kidney in participants with diabetes." (PMID 35888152, 2022). "On the other hand, inducible overexpression of Smad7 in adult mice causes overt diabetes with hypoinsulinemia, impaired glucose tolerance, and reduced pancreatic insulin content." (PMID 35327565, 2022). "Additionally, miR21-5p and miR-96-5p target SMAD7, which is linked to “fibrosis of the liver”, “proliferation of liver cells”, “proliferation of hepatocytes”, “diabetes mellitus”, and “glucose metabolism disorder”." (PMID 37511368, 2023). "In contrast, the mRNA expression of Smad7 was significantly upregulated in SBECD + OTX + CHR group by 12.7-fold compared to diabetes." (PMID 38169923, 2023). "Overt diabetes is also observed in adult mice with conditional Smad7 overexpression under the RIP promoter using the doxycycline-inducible Tet-On system." (PMID 35327565, 2022). "The huoxue component can inhibit TGF-β1 signaling by targeting SMAD7 to regulate the establishment and maintenance of mature pancreatic β cells, which is closely related to reversible diabetes." (PMID 30521536, 2018). "Further, our results show that elevated levels of inhibitory SMAD7 contribute to the delayed response of the lung to the effects of diabetes." (PMID 30093732, 2018). "In our studies, decreased levels of SMAD7 in the diabetic lung compared to those in the control lung confirmed the presence of diabetes-induced TGF-β1 signaling in the lung." (PMID 30093732, 2018). "Smad7 also participates in beta cell function and insulin secretion, since overexpression of Smad7 in beta cells results in reversible diabetes in mice." (PMID 30322036, 2018). "The gradual increase in the levels of TGF-β1, ICAM-1, and phospho-p38, with a concurrent time-dependent decrease in SMAD7 levels, suggested that diabetes-induced fibrotic changes began at 8 wk postinduction." (PMID 30093732, 2018). "SMAD7 protein expression in the renal cortex is decreased in diabetes and conditional expression of SMAD7 in pancreatic β cells disrupts TGF-β signaling and induces reversible diabetes mellitus." (PMID 23560096, 2013). "For example, transferrin receptor (TFRC), hemochromatosis (HFE), and heme oxygenase 1 (HMOX1) are associated with an increased risk of diabetes, while transmembrane protease, serine (TMPRS), and mothers against decapentaplegic homolog 7 (SMAD7) are associated with a decreased risk." (PMID 40871742, 2025). "Moreover, while Smad7 induces beta-cell proliferation in the PDL and ppx models of diabetes, the overexpression of Smad7 in beta cells induces a reversible diabetic phenotype." (PMID 37623211, 2023). "However, more evidence is warranted to clarify the exact role of Smad7 in β cell function and diabetes." (PMID 35327565, 2022). "In addition, we also identified a better inhibitory effect of AANG on NF-κB inflammatory pathway in the diabetic kidney due to its synergistic induction of Smad7 expression." (PMID 36147472, 2022). "To test this hypothesis, we examined SMAD7 levels in the lung at 4, 8, and 12 wk after diabetes induction." (PMID 30093732, 2018). "The miR-181c levels of elderly patients with frailty who present with diabetes mellitus and heart failure with preserved ejection fraction were significantly high, and miR-181c targeted PRKN and SMAD7 in human cardiac fibroblasts." (PMID 39444490, 2024). "Under the conditions of high glucose and diabetes, miR-21 controls p-Smad3 (Ser423/425), EMT, and ECM deposition modulation through Smad7." (PMID 35865316, 2022). "Taken together, our results demonstrate for the first time that diabetes induces fibrotic changes in the lung via TGF-β1-activated EMT pathways and that elevated SMAD7 partially protects the lung during the initial stages of diabetes." (PMID 30093732, 2018).
diabetes (continued). "We observed that there was no significant change in the level of SMAD7 compared to the level in the control until 8 wk after diabetes induction." (PMID 30093732, 2018). "To determine if the delayed response of the lung was due to the presence of higher SMAD7 levels or lower TGF-β1 levels in the lung than in the kidney, we compared the TGF-β1 levels in the diabetic lung, kidney and liver with those in the respective controls after 8 wk of diabetes induction." (PMID 30093732, 2018).
Crohn disease (20 papers, 2006 to 2026). A gastrointestinal disorder characterized by chronic inflammation involving all layers of the intestinal wall, noncaseating granulomas affecting the intestinal wall and regional lymph nodes, and transmural fibrosis. "And in the early stage of Crohn’s disease, Smad7 is expressed in a large number of cells in the epithelium and lamina propria of the new terminal ileal mucosa, and the use of Smad7 blocker is helpful to prevent postoperative recurrence." (PMID 37875976, 2023). "Previous research on Crohn’s disease has shown that drugs like Mongersen, which reduces the expression of SMAD7, can help treat the inflammation." (PMID 29415065, 2018). "Interestingly, inhibitory-SMAD (SMAD7) protein levels have been found to be increased in mucosal biopsy samples of patients with Crohn’s disease when compared to healthy controls." (PMID 33834163, 2019). "Phase 1 clinical trials of oral Smad7 knockdown therapy demonstrated clinical safety and a double-blind phase 2 trial found that patients with Crohn’s disease who received Smad7 knockdown therapy had significantly higher rates of remission and clinical response than those who received the placebo." (PMID 33834163, 2019). "Our data showing a relationship between SMAD7 and IL-1R1 expression in PSCs is also consistent with recent data demonstrating decreased inflammation and clinical benefits for patients with active Crohn’s disease after blocking SMAD7 by a SMAD7 anti-sense oligonucleotide." (PMID 27473228, 2016). "Overexpression of Smad7 and unresponsiveness to TGF-β1 also characterized lamina propria mononuclear cells in gut from patients suffering from Crohn's disease." (PMID 16800882, 2006). "The likely contribution of SMAD7 activation to the observed TGF-β pathway inhibiton in CML LSCs compared to normal HSCs and the current clinical investigation of antisense oligonucleotides for SMAD7 inhibition in Crohn's disease make it an attractive target for CML LSC-directed therapy." (PMID 23651669, 2013). "The high SMAD7 immunoreactivity and lack of p-SMAD3 expression in the LP suggests defective TGF-β signaling in the LP in EE similar to a previously reported SMAD7-mediated inflammatory pathway in refractory CD and Crohn’s disease." (PMID 29415065, 2018).
liver cancer (19 papers, 2008 to 2025). An epithelial or non-epithelial malignant neoplasm that arises from the liver. "We tried to find out the potential common miRNA target for Smad7 and circFGGY, which is associated with liver cancer." (PMID 35592246, 2022). "As SMAD7 was downregulated in liver cancer and was associated with malignant disease, we explored its role as a cancer suppressor in liver cancer." (PMID 31711043, 2019). "SMAD7 expression was higher in normal tissues than in liver cancer tissues, suggesting that the down-regulation of SMAD7 was associated with liver cancer progression." (PMID 31711043, 2019). "Similar findings were obtained in HCC tissues from female p53LKO mice: high TfR1 and low mRNA expression of Hamp, Hfe, Smad7, Bmp6, and Ferroprotin (Fpn1), were observed in liver cancer tissues in comparison to NTL." (PMID 39820815, 2025). "Shikonin inhibited cell progression and EMT and accelerated cell death by regulating the miR-106b/Recombinant Mothers Against Decapentaplegic Homolog 7 (SMAD7)/TGF-β signaling pathway to achieve the desired therapeutic effect in liver cancer treatment." (PMID 38138440, 2023). "In clinical trials, we found that in the cancer tissues of HCC patients, the expression of Smad7 decreased, while the expression of miR-21-5p increased, indicating that miR-21-5p promoted the development of liver cancer." (PMID 35518787, 2022). "In order to further study the relationship between Smad7 and miR-21-5p, we transfected liver cancer cells with miR-21-5p mimics or inhibitors for 48 hours." (PMID 35518787, 2022). "To investigate the biological function of SMAD7 in liver cancer, we initially re-measured the relative mRNA expression of SMAD7 in 8 paired liver cancer tissues." (PMID 31711043, 2019). "Because SMAD7 expression is less in liver cancer cells, detecting the protein level of SMAD7 was difficult." (PMID 31711043, 2019). "In the present study, we found that the mRNA and protein expression of SMAD7 in liver cancer tissues was significantly down-regulated compared to that in the adjacent normal tissues, as well as in liver cancer cell lines." (PMID 31711043, 2019). "Next, we analyzed the correlation between the expression level of SMAD7 and the clinical features of patients with liver cancer." (PMID 31711043, 2019). "We found that the expression level of SMAD7 was lower in the liver cancer cell lines than in HL-7702 (p<0.001)." (PMID 31711043, 2019). "Two independent studies have demonstrated that the expression level of Smad7 is significantly reduced in some cohorts of liver cancer tissues when compared with normal tissues." (PMID 31614569, 2019). "Taken together, these results strongly suggest that SMAD7 is involved in Tan IIA-induced liver cancer apoptosis in vivo and in vitro." (PMID 31711043, 2019). "Subsequently, we detected SMAD7 protein expression in 4 human liver cancer cell lines and in the normal liver epithelial cell line HL-7702." (PMID 31711043, 2019). "The overexpression of SMAD7-Flag in liver cancer cells largely induced cell apoptosis and inhibited cell growth and migration in vitro and in vivo." (PMID 31711043, 2019). "Our findings suggested that Tan IIA can significantly inhibit liver cancer cell growth and migration in vivo and in vitro by regulating SMAD7-YAP expression in a TGF-β/SMAD signaling pathway-dependent manner." (PMID 31711043, 2019). "miR-216a/217 promote EMT, drug resistance and recurrence of liver cancer by targeting Smad7 and PTEN, which inhibit TGF-β and PI3K/Akt signaling, respectively." (PMID 31614569, 2019). "To better understand the biological function of SMAD7 in inhibiting liver cancer development and progression, we generated a protein–protein interaction network for SAMD7 by using the cBioPortal database." (PMID 31711043, 2019). "Taken together, our results suggest that Tan IIA can upregulate SMAD7 to promote E3 ligase βTrcp expression that can promote YAP protein degradation in liver cancer." (PMID 31711043, 2019).
liver cancer (continued). "We also performed immunohistochemistry (IHC) to detect SMAD7 staining in normal and liver cancer tissues." (PMID 31711043, 2019). "Further, we found that Tan IIA promoted liver cancer cell apoptosis as well as suppressed cell proliferation, invasion, and migration by up-regulating SMAD7 mRNA and protein expression in vivo and in vitro." (PMID 31711043, 2019). "In this study, we found that SMAD7 expression was reduced in liver cancer tissues, as well as liver cancer cell lines." (PMID 31711043, 2019). "Although contradicting with those obtained in two other studies, these results suggest that the expression and function of Smad7 in liver cancer are highly reliant on contexts, such as developing stage and cancer subclassification." (PMID 31614569, 2019). "In keeping with its critical roles in regulating TGF-β signaling and in liver cancer, Smad7 gene expression is tightly regulated in liver cancer by contextual transcription factors and co-factors." (PMID 31614569, 2019). "Next, CP assay revealed that SMAD7 can bind to endogenous YAP in the liver cancer cell lines overexpressing SMAD7-Flag." (PMID 31711043, 2019). "In advanced liver cancer, Smad7 is able to inhibit TGF-β-induced expression of Snail, a master transcription factor in EMT, alleviating HCC formation in mouse liver." (PMID 31614569, 2019). "In this study, we found that Tanshinone IIA mediates SMAD7-YAP interaction to induce liver cancer cell apoptosis and inhibit cell growth and migration by inactivating the transforming growth factor beta (TGF-β) signaling pathway." (PMID 31711043, 2019). "Taken together, our findings suggested that Tan IIA can suppress liver cancer cell growth, migration, and invasion as well as promote cell apoptosis; it plays a role as an antitumor agent by regulating the expression of SMAD7-YAP." (PMID 31711043, 2019). "Autocrine IL-6 signaling is critical for liver cancer progenitor cell-related disease progression, suggesting future analysis of progenitor cell effects in SMAD7-dependent HCC." (PMID 28134936, 2017). "We then defined a link between SMAD7 expression and STAT3 signaling in liver cancer by detecting increased pSTAT3 expression in liver tissue of SMAD7 KO mice." (PMID 28134936, 2017). "To explore the role of liver cancer-related genes in tumorigenesis, we performed medium-throughput PCR assay to detect the mRNA expression level of these genes in human liver cancer tissues and found a series of differentially expressed genes, including SMAD7." (PMID 31711043, 2019). "In conclusion, to our knowledge, this is the first study to show that Tan IIA can inhibit liver cancer proliferation, migration, and invasion as well as promote cell apoptosis by regulating the expression of SMAD7 and YAP in a TGFβ signaling pathway-dependent manner." (PMID 31711043, 2019). "Taken together, these data indicated that SMAD7 is important for inhibiting human liver cancer cell growth and migration and might play a role of a tumor suppressor gene in liver cancer." (PMID 31711043, 2019). "To further determine the biological role of SMAD7 in liver cancer cells, we investigated the effect of the overexpression of SMAD7-Flag and found that this markedly decreased the cell growth ability compared with that of the control in Bel-7404 and SMMC-7721 cells (*p=0.0110<0.05, **p=0.0026<0.01)." (PMID 31711043, 2019). "On the other hand, mounting evidence has pointed out that Smad7 may act as a tumor suppressor in liver cancer by interfering with the oncogenic effects of TGF-β or other tumor-promoting pathways." (PMID 31614569, 2019). "Furthermore, we found that the overexpression of SMAD7 impaired the migration ability of liver cancer cells (**p=0.0021<0.01, ***p<0.001) and enhanced their apoptosis rate, which was indicated using the cleaved caspase substrate." (PMID 31711043, 2019).